DNAJC10 (DnaJ heat shock protein family (Hsp40) member C10)
Diseases named in the same sentence as DNAJC10 in open-access papers:
DNAJC10 is named in the same sentence as 36 diseases in open-access papers, as found by Europe PMC text mining. Sharing a sentence is not in itself a finding about the gene and the disease. The quoted sentences say what the papers report.
glioma (7 papers, 2020 to 2025). A benign or malignant brain and spinal cord tumor that arises from glial cells (astrocytes, oligodendrocytes, ependymal cells). "Further, the significance of DNAJC10 expression varies among different cancers; for example, high DNAJC10 expression is associated with poor prognosis in patients with glioma, while DNAJC10 mRNA downregulation predicts weak OS and relapse‐free survival in patients with breast cancer." (PMID 39031896, 2024). "Moreover, subgroup survival analysis revealed that overexpression of DNAJC10 was still associated with poorer OS of LGGs (log-rank test) or GBMs (log-rank test) in all three glioma cohorts." (PMID 34988580, 2022). "We reveal the prognostic role and underlying functions of DNAJC10 in glioma in the present study." (PMID 34988580, 2022). "For further excavating the underlying correlated functions, pathways and tumor hallmarks, we performed differential expression analysis (DEA) between low-DNAJC10 subgroup gliomas and high-DNAJC10 subgroup to identify DEGs associated with DNAJC10 expression (FDR < 0.05) in the TCGA glioma cohort." (PMID 34988580, 2022). "To determine DNAJC10’s role in glioma, we first assessed its expression in clinical specimens using the Human Protein Atlas (HPA)." (PMID 41191192, 2025). "To address small sample size limitations, we expanded via the #HBraG177Su01 microarray dataset (including low-grade gliomas), which showed lower DNAJC10 correlated with poorer survival across all glioma grades." (PMID 41191192, 2025). "GSEA results displayed DEGs expressed at lower level in DNAJC10-OE group were enriched in the “regulation of glial cell migration” gene set, again supporting DNAJC10 overexpression suppresses glioma cell migration." (PMID 41191192, 2025). "We also observed a relationship between high DNAJC10 expression and poor OS in patients with LC, consistent with a report of the effect of DNAJC10 in glioma." (PMID 39031896, 2024). "Immune/stromal cell infiltrations, tumor mutation burden (TMB), copy number alteration (CNA) burden and immune checkpoint genes (ICPGs) were also positively correlated with DNAJC10 expression in gliomas." (PMID 34988580, 2022). "To better illustrate the clinical significance of aberrant expression of DNAJC10, we did survival analysis (Kaplan–Meier method) and ROC curves to evaluate the prognostic role and prognosis predictive power of DNAJC10 in gliomas." (PMID 34988580, 2022). "Immune/Stromal scores represent the infiltrations of immune/stromal cells in tumor tissues, and the results indicated that gliomas with higher DNAJC10 expression were correlated with higher immune score, stromal score, TMB, CNA burden and ICPG expressions." (PMID 34988580, 2022). "DEGs between low- and high-DNAJC10 gliomas were identified to perform functional annotations to uncover the potential functions of DNAJC10 in glioma." (PMID 34988580, 2022). "For further validating the conclusion, we analyzed the DNAJC10 expression in the TISCH website, an integrated single-cell RNA dataset, the results revealed that DNAJC10 is mainly expressed in GBM cells in the microenvironment of gliomas." (PMID 34988580, 2022). "The overall survival (OS) of glioma patients with different DNAJC10 expression was compared by Kaplan–Meier method (two-sided log-rank test)." (PMID 34988580, 2022). "The images showed that the DNAJC10 was mainly located at cytoplasm and cell membrane of glioma cells." (PMID 34988580, 2022). "The mRNA expression of DNAJC10 was up-regulated in gliomas and it was strongly correlated with glioma clinicopathological features." (PMID 34988580, 2022). "To visualize the DNAJC10 protein localization in glioma cells, we performed immunofluorescence assay of DNAJC10 in U87 glioma cell line." (PMID 34988580, 2022). "Herein, we systematically assessed the potential role of DNAJC10 in gliomas using several bioinformatics and experimental methods." (PMID 34988580, 2022).
glioma (continued). "Bioinformatics results revealed that both mRNA and protein of DNAJC10 were up-regulated in gliomas, and the qRT-PCR and Western blot assays of our collected clinical samples got the same conclusion." (PMID 34988580, 2022). "Clinically, glioma patients with higher DNAJC10 expression present poorer prognosis and it showed a stable predictive accuracy in predicting 1/3/5-OS of glioma patients." (PMID 34988580, 2022). "Given the aberrant high expression of DNAJC10 in gliomas, we then analyzed the different expression levels of DNAJC10 between/among different clinicopathological features of gliomas." (PMID 34988580, 2022). "In current research, we collected 3 independent glioma cohorts and 12 GBM samples and found that the messenger RNA (mRNA) and protein expressions of DNAJC10 are both up-regulated in glioma." (PMID 34988580, 2022). "The results from the three independent glioma cohorts showed that the DNAJC10 expressions were up-regulated in higher WHO grade gliomas (Wilcoxon rank-sum test), which was consistent with the result of IHC images from HPA dataset." (PMID 34988580, 2022). "Several bioinformatics datasets, including GTEx, TCGA and CGGA, HPA datasets, were used to determine the relative expression levels of DNAJC10 in gliomas." (PMID 34988580, 2022). "Enrichment analysis recognized that T-cell activation and T-cell receptor signaling were enriched in higher DNAJC10 gliomas." (PMID 34988580, 2022). "Survival curves analysis indicated that glioma patients with higher expression levels of DNAJC10 survive shorter than lower group in the three independent glioma patients (log-rank test)." (PMID 34988580, 2022). "DNAJC10 was highly expressed in most cancers but largely undetected in gliomas." (PMID 41191192, 2025). "Recently, DNAJC10 was reported to participate in glioma, breast cancer, and neuroblastoma." (PMID 39031896, 2024). "The DNAJC10 protein expression increased with the increase of WHO glioma tumor grade." (PMID 36358853, 2022). "Furthermore, 12 reported ICPG expression levels were also compared between low-DNAJC10 and high-DNAJC10 glioma subgroups." (PMID 34988580, 2022). "Subsequently, Kaplan–Meier curves analysis was performed in three glioma cohorts from public datasets, and results revealed that mRNA expression of DNAJC10 could delaminate glioma patients into long- and short-OS subgroups." (PMID 34988580, 2022). "In functional annotation analysis, DNAJC10 showed a significant correlation with glioma immune infiltrations and we speculated that it might be attributed to the functions of substrate proteins that DNAJC10 catalyzes intracellularly." (PMID 34988580, 2022). "Especially, the expression of DNAJC10 was up-regulated with the WHO grade increasing, which indicated that the expression of DNAJC10 might be associated with the malignance of gliomas." (PMID 34988580, 2022). "Thus, we performed a systemic and multicohort prognostic analysis of DNAJC10 to reveal its risky role in glioma patients." (PMID 34988580, 2022). "We noticed that T-cell activation, T-cell complex and T-cell signaling pathway were annotated in high-DNAJC10 glioma subgroup, thus we speculated that DNAJC10 might play a role in cancer immunity." (PMID 34988580, 2022). "Gliomas with higher DNAJC10 expression present poorer prognosis compared with low-DNAJC10 gliomas." (PMID 34988580, 2022). "Besides, high DNAJC10 expression was also significantly associated with MGMT unmethylated status (Wilcoxon rank-sum test), IDH wild status (Wilcoxon rank-sum test) and 1p/19q non-codeletion status (Wilcoxon rank-sum test) in gliomas." (PMID 34988580, 2022). "Immunohistochemistry (IHC) of 107 clinical brain specimens revealed DNAJC10 was largely undetected or reduced in GBM (WHO grade 4) samples, but prevalent in low-grade gliomas." (PMID 41191192, 2025).
glioma (continued). "Besides, we detected the DNAJC10 protein expression of the 12 clinical samples using Western blot assay, consistent with the qRT-PCR results, the DNAJC10 protein was also overexpressed in glioma samples and up-regulated with the WHO grades increasing (Student’s t test)." (PMID 34988580, 2022). "Remarkably, the downregulated DEGs in DNAJC10-OE group were also enriched in cell adhesion, ECM organization, and positive regulation of cell migration, suggesting DNAJC10 overexpression suppresses glioma cell migration." (PMID 41191192, 2025). "For certain HSPs representatives (i.e., HSP10, HSPB1, DNAJC10, HSPA7, HSP90), a direct correlation between the protein level expression (based on IHC analysis) and poor overall survival prognosis for patients with glial tumors was identified." (PMID 36358853, 2022).
breast carcinoma (4 papers, 2018 to 2024). "In addition, DNAJC10 mRNA expression also reduced significantly in breast cancer cells (BT-20, MDA-MB-231, and ZR-75-1), and was associated with better overall survival and relapse-free survival in breast cancer." (PMID 38255948, 2024). "However, the role of DNAJC10 in breast cancer and neuroblastoma was reported to be a protective factor or cancer suppressor, which was distinct with our results." (PMID 34988580, 2022).
neuroblastoma (4 papers, 2020 to 2025). Neuroblastoma (NB) is the most common solid, extracranial childhood tumor. "This aligns with DNAJC10’s tumor-suppressive roles in prostate, neuroblastoma, and colon cancer via modulating UPR." (PMID 41191192, 2025).
Parkinson disease (3 papers, 2017 to 2022). A progressive degenerative disorder of the central nervous system characterized by loss of dopamine producing neurons in the substantia nigra and the presence of Lewy bodies in the substantia nigra and locus coeruleus. "DNAJC10 is a member of the DNAJC protein family, a subclass of heat shock proteins; mutations of these proteins may be related to Parkinson's disease (as they are a feature of Parkinson's disease and other neurological diseases)." (PMID 35841000, 2022).
Huntington disease (2 papers, 2016 to 2021). Huntington disease (HD) is a rare neurodegenerative disorder of the central nervous system characterized by unwanted choreatic movements, behavioral and psychiatric disturbances and dementia. "ER luminal protein dnj-27, a mammalian DNAJC10 ortholog, showed a protective role against PD, Alzheimer and Huntington diseases in transgenic Caenorhabditis elegans models." (PMID 27653456, 2016).
leukemia (1 paper, 2025). A malignant (clonal) hematologic disorder, involving hematopoietic stem cells and characterized by the presence of primitive or atypical myeloid or lymphoid cells in the bone marrow and the blood. "However, DNAJC10 also promotes leukemia stem cell self-renewal during ER stress, and its knockdown reduces proliferation in lung adenocarcinoma, indicating its context-dependent oncogenic roles." (PMID 41191192, 2025).
cancer (7 papers, 2007 to 2025). A tumor composed of atypical neoplastic, often pleomorphic cells that invade other tissues. "The Cancer Genome Atlas Program (TCGA) GBM datasets further showed decreased DNAJC10 mRNA linked to shorter OS and DFS." (PMID 41191192, 2025). "Emerging evidence implicates DNAJC10 in cancer processes including apoptosis, proliferation, autophagy, migration, and invasion, though its role in GBM remains poorly defined." (PMID 41191192, 2025). "DnaJ Heat Shock Protein Family (Hsp40) Member C10 (DNAJC10, also known as ERDJ5 and PDIA19), involved in endoplasmic reticulum-associated degradation (ERAD), has been identified as a tumor suppressor in several cancers." (PMID 41191192, 2025). "Given its role in regulating protein quality control, DNAJC10 balances cell survival and apoptosis, influencing cancer progression." (PMID 41191192, 2025). "Further analysis demonstrated DNAJC10 overexpression significantly reduced cancer cells numbers at the tumour invasive frontier (defined as 200 μm from the tumor edge)." (PMID 41191192, 2025). "MCM8 expression was positively correlated with that of DNAJC10 in LC samples from The Cancer Genome Atlas database, and DNAJC10 upregulation was also associated with poor overall survival of patients with LC." (PMID 39031896, 2024). "Hence, further studies are needed to explore the role of DNAJC10 in cancer as a ‘‘friend or foe’’ and to elucidate its clinical significance in difference cancers." (PMID 41191192, 2025). "This information could provide us some useful clues for further excavating potential mechanisms of DNAJC10 in cancer progression." (PMID 34988580, 2022). "Importantly, RNA-seq indicated DNAJC10 downregulates CAMs-related genes such as ITGAV, SEMA3C, DPP4, and ITGA1, which promote cancer cell migration and invasion." (PMID 41191192, 2025). "Furthermore, Heatmap analysis showed DNAJC10 overexpression reduced transcription of CAMs related genes such as ITGAV, SEMA3C, DPP4, and ITGA1, which are reported to enhance cancer cell migration and invasion." (PMID 41191192, 2025). "RNA-seq also revealed DNAJC10’s involvement in cancer-related pathways, including but not limited to focal adhesion, ECM-receptor interaction, PI3K-Akt signaling, regulation of actin cytoskeleton, and MAPK signaling pathway." (PMID 41191192, 2025).
tumor (7 papers, 2018 to 2025). "The GO and KEGG results of top 1000 up-regulated DEGs revealed a potential correlation between DNAJC10 and T-cell activation and T-cell receptor signaling; this motived us to investigate the associations between DNAJC10 and tumor immune characteristics." (PMID 34988580, 2022). "Furthermore, the DNAJC10 expression was also correlated with most of immune characteristics, immune and stromal scores, tumor mutation burden (TMB), copy number alteration (CNA) burden, and 12 immune checkpoint gene (ICPG) expressions." (PMID 34988580, 2022). "We proposed DNAJC10 as a tumor suppressor based on its downregulation correlating with poor patient outcomes, supression of migration and invasion, and inhibition of tumor propagation in xenografts." (PMID 41191192, 2025). "Strikingly, DNAJC10-OE A172 xenografts displayed significantly reduced tumor infiltration and prolonged survival compared to Vector controls, mirroring results from wild-type EGFR-expressing U87 models." (PMID 41191192, 2025). "HSPA5 is a key regulator of the UPR and has significant implications in cell survival and tumor progression, while reports on the roles of DNAJC10 in tumorigenesis are limited." (PMID 40765821, 2025). "Additionally, Clinical Proteomic Tumor Analysis Consortium (CPTAC) proteogenomic GBM dataset confirmed higher DNAJC10 protein levels correlated with longer OS and recurrence-free survival (RFS)." (PMID 41191192, 2025). "We found that DNAJC10 appears to act as a novel tumor suppressor gene in GBM." (PMID 41191192, 2025). "Western blot revealed DNAJC10 overexpression significantly reduced XBP-1s protein levels in GBM cells and in vivo tumours." (PMID 41191192, 2025). "In conclusion, DNAJC10 inhibits GBM migration, invasion, and tumor propagation in vitro and in vivo by targeting EGFR." (PMID 41191192, 2025). "Clinically, DNAJC10 downregulation correlates with poor GBM survival, highlighting its tumor-suppressive role by disrupting XBP-1s–EGFR axis." (PMID 41191192, 2025). "Together, these results demonstrate DNAJC10 overexpression inhibits GBM progression across different EGFR genetic backgrounds, highlighting its robust in vivo tumor-suppressive activity." (PMID 41191192, 2025). "DNAJC10, RNF149 and STYXL1 all harbored significantly higher mRNA expression levels in tumor tissues compared to normal prostate." (PMID 29890952, 2018). "Moreover, DNAJC10 overexpression inhibits infiltrative growth of GBM cells, suppresses tumor propagation and prolongs survival in xenografted mice." (PMID 41191192, 2025). "Furthermore, our IHC staining analysis showed that the expression of MCM8, DNAJC10 and Ki67 were all decreased in MCM8 knock down xenograft model‐derived tumours compared with control." (PMID 39031896, 2024). "None of the other genes DNAJC10, RNF149 or STYXL1 had a significant effect on tumor growth or tumor weight." (PMID 29890952, 2018).
infection (2 papers, 2016 to 2023). The state of being infected such as from the introduction of a foreign agent such as serum, vaccine, antigenic substance or organism. "According to our analysis above, the difference between YN13 and YN144 in replication ability might be due to the difference between the two PEDV-infection groups in alterations of eIF4G1, hnRNPA1, HSP90B1, HSP90AB1, HSPA8, DNAJA1, and DNAJC10 in jejunums of pigs." (PMID 27916855, 2016).
DNAJC10 also shares sentences with these, for which no sentence is quoted: Sjögren’s syndrome (4 papers); colitis (2); colon cancer (2); neurodegenerative disease (2); neuroectodermal tumors (2); neurological diseases (2); Alzheimer disease (1); Autoimmunity (1); brain cancer (1); dementia (1); ER stress (1); essential hypertension (1); glioblastoma (1); Hypercholesterolemia (1); inflammatory bowel disease (1); lung adenocarcinoma (1); lung carcinoma (1); melanoma (1); neutropenia (1); osteosarcoma (1); prostate adenocarcinoma (1); pulmonary arterial hypertension (1); retinal degeneration (1); retinal disease (1); sarcoma (1); squamous cell carcinoma (1); xerostomia (1).